PARP6 (poly(ADP-ribose) polymerase family member 6)
Description:
Mono-ADP-ribosyltransferase that mediates mono-ADP-ribosylation of target proteins.
Synonyms: ARTD17; pART17; PARP-6-B1; PARP-6-C
Tractability: Small molecule: a high-quality ligand is known. Antibody: the Human Protein Atlas places it where antibodies can reach. PROTAC: ubiquitination databases record sites on it; a small molecule that binds it is known.
Target class: Enzyme; Transferase
Chemical probes: AZ0108 (high quality)
Gene: Protein-coding gene on chromosome 15 (72,241,176 to 72,272,999, reverse strand). Ensembl gene ENSG00000137817.
Subcellular location (Human Protein Atlas): Plasma membrane
Pathways (Reactome):
Disease: Maturation of nucleoprotein
Metabolism: Nicotinate metabolism
Gene Ontology:
Molecular function: NAD+-protein-aspartate ADP-ribosyltransferase activity; NAD+-protein-cysteine ADP-ribosyltransferase activity; kinase binding; NAD+ poly-ADP-ribosyltransferase activity; protein serine/threonine kinase activator activity
Biological process: protein auto-ADP-ribosylation; endoplasmic reticulum unfolded protein response; positive regulation of dendrite morphogenesis
Cellular component: endoplasmic reticulum tubular network; membrane; nuclear envelope
Genetic constraint (gnomAD): Loss-of-function variants: 16 observed, 53.85 expected, observed/expected ratio (o/e) 0.3, 90% interval 0.2 to 0.45. The upper end of that interval is the gene's LOEUF score, 0.45, which puts it in group 2 of 6, group 1 being the genes least tolerant of losing a copy. Missense variants: 427 observed, 651.03 expected, observed/expected ratio (o/e) 0.66, 90% interval 0.61 to 0.71. Synonymous variants: 216 observed, 237.7 expected, observed/expected ratio (o/e) 0.91, 90% interval 0.81 to 1.02.
Homologues: Orthologues: chimpanzee PARP6 (100% identical), dog PARP6 (100% identical), rabbit PARP6 (99% identical), guinea pig PARP6 (99% identical), pig PARP6 (97% identical), mouse Parp6 (97% identical), rat Parp6 (96% identical), macaque PARP6 (93% identical), tropical clawed frog parp6 (85% identical), zebrafish parp6b (77% identical), zebrafish parp6a (26% identical). Paralogues in human: PARP8 (62% identical), PARP16 (13% identical).